TNF (tumor necrosis factor)
Diseases named in the same sentence as TNF in open-access papers (continued):
Sharing a sentence is not in itself a finding about the gene and the disease.
posterior uveitis (9 papers, 2016 to 2025). Inflammation of the choroid as well as the retina and vitreous body. "Given the persistence of bilateral posterior uveitis despite the control of systemic inflammation, we chose tumor necrosis factor inhibitor (anti-TNF) therapy because it has already proven to be beneficial in non-infectious uveitis." (PMID 41200126, 2025). "Therapies for posterior uveitis are limited to corticosteroids, cyclosporine and tumour necrosis factor (TNF)-blocking agents as well as off-label use of methotrexate, azathioprine and mycophenolates." (PMID 33671954, 2021). "The patient had two episodes of flare-up of posterior uveitis, the initial one possibly due to a sub-optimal immunosuppressive regime that allowed the persistence of inflammatory cytokines such as TNF-alpha, which was subsequently addressed with adalimumab and systemic methotrexate." (PMID 39246872, 2024). "Although anti-TNFα drugs are approved for many other chronic immune-mediated inflammatory diseases, they are still used off-label for non-infectious posterior uveitis, with the exception of adalimumab which has been approved for this indication." (PMID 33671954, 2021). "Master inflammatory cytokine, tumor necrosis factor-alpha (TNF-α), plays an important role in the progression of noninfectious posterior uveitis." (PMID 27293321, 2016).
pressure ulcers (9 papers, 2015 to 2025). "In stage 1 pressure ulcers on the sacrum, IL-1β, IL-6, IL-8, TNF-α and IFN-γ were found to be upregulated." (PMID 39772735, 2025). "Similar to mupirocin, mice treated with oral clindamycin exhibited a decrease in expression of IL-1β (−1.32-fold change), MMP-2 (−1.37-fold change), and TNF-α (−2.80-fold change) in infected pressure ulcers." (PMID 34035383, 2021). "At day 6 post‐I/R, H2 treatment significantly reduced the relative mRNA and protein expression of TNF‐α, IL‐1β, IL‐6 and IL‐8 in wounded tissue, and their expression was lowest in pressure ulcer mice treated with 75% H2." (PMID 29921037, 2018). "Elevations in NFκB, TNFα, and NOS2 have been seen during the development of pressure ulcers in murine models, and are thought to contribute to the sustained pro-inflammatory immune response seen in these chronic wounds." (PMID 33374656, 2020). "Some studies have reported that elevated levels of TNF-α and a suite of proinflammatory cytokines may be observed by patients in patients with chronic SCI, especially in patients with pain, UTIs, and pressure ulcers." (PMID 37108209, 2023). "In diabetic wounds, elevations in IL-6 and TNFα further lowers dermal fibroblast proliferation through downregulation of PI3K/AKT activity, resulting in impaired collagen deposition and wound contracture, although this interaction is not fully elucidated in pressure ulcer pathophysiology." (PMID 33374656, 2020).
primary sclerosing cholangitis (9 papers, 2017 to 2024). "Another study revealed the possible association between the altered function of T cells and increased tissue level of TNF-α in patients with primary sclerosing cholangitis." (PMID 28299346, 2017). "Higher excess risks were found among patients with NHL with concomitant primary sclerosing cholangitis (SIR 3.4; 95% CI 2.1 to 5.2) and in those prescribed thiopurines alone (SIR 2.8; 95% CI 1.4 to 5.7) or with anti-TNF-α agents (SIR 5.7; 95% CI 2.7 to 11.9)." (PMID 37142293, 2023). "Pro-inflammatory Th1 cytokines, such as tumor necrosis factor-alpha (TNF-α) and interferon-gamma (IFN-γ), are induced in primary sclerosing cholangitis, PSC, and biliary atresia." (PMID 32846954, 2020).
renal clear cell carcinoma (9 papers, 2016 to 2025). "Specifically, the patients who developed renal clear cell carcinoma and hepatic T-cell lymphoma had their malignancies develop remote from anti-TNF usage." (PMID 29540190, 2018). "Clear-cell renal cell carcinoma (ccRCC), a tubular epithelial malignancy, secretes tumor necrosis factor (TNF), which signals ccRCC cells in an autocrine manner via two cell surface receptors, TNFR1 and TNFR2, to activate shared and distinct signaling pathways." (PMID 38537932, 2024). "In patients with clear cell renal cell carcinoma, CD39 + CD8 + T cells exhibited a dampened production of pro-inflammatory cytokines TNF-α and IFN-γ alongside increased expression of inhibitory markers PD-1 and TIM-3." (PMID 38703294, 2024). "IL2-XE114-TNFmut may thus be considered as a promising biopharmaceutical for the treatment of metastatic clear-cell renal cell carcinoma, since these tumors are known to be sensitive to IL2 and to TNF." (PMID 31799191, 2019). "We previously reported that renal clear cell carcinoma cells (RCC) express both tumor necrosis factor receptor (TNFR)-1 and -2, but that, in organ culture, a TNF mutein that only engages TNFR1, but not TNFR2, causes extensive cell death." (PMID 27362805, 2016).
Senile plaques (9 papers, 2013 to 2022). Senile plaques are extracellular deposits of amyloid in the gray matter of the brain. "IL1A, IL1B, IL2, IL8, IFNγ, and TNFα have been found to be associated with senile plaques." (PMID 25197660, 2014). "One with high expression levels of IL-1β, TNF-α and IL-12A typical of a pro-inflammatory phenotype related with oligomeric Aβ, the other located near senile plaques with upregulation of IL-1ra, Arginase 1 and FIZZ, is characteristic of a reparative phenotype." (PMID 35011699, 2022). "In the brains of AD patients, microglial activation is observed in the vicinity of senile plaques at all stages of the disease and is accompanied by increased levels of proinflammatory molecules (e.g., TNF, IL-1β, IL-6, prostaglandins)." (PMID 34228639, 2021). "In neurodegeneration, TNF-α induces neuronal excitotoxic injury (via glutamate), accumulates around senile plaques, and it can also increase synaptic transmission." (PMID 30186149, 2018). "TNF-α- and iNOS-positive microglia infiltrated into senile plaques in the hippocampus." (PMID 24152138, 2013). "The gathered microglia towards senile plaques induce the formation of Aβ deposits rather than clearance due to excessive inflammatory cytokines such as IFN-γ and TNF-α." (PMID 35006402, 2021).
Skeletal muscle atrophy (9 papers, 2011 to 2025). The presence of skeletal muscular atrophy (which is also known as amyotrophy). "Pro-inflammatory cytokine TNF-α plays a pivotal role in mediating cancer-related skeletal muscle degeneration." (PMID 24302570, 2013). "TNF-α levels are increased during cachectic muscle wasting (exerted through inhibition of myogenic differentiation and enhanced apoptosis) and chronic muscle degeneration, inflammatory myopathies and regeneration processes which are linked to primary muscle disorders." (PMID 36230365, 2022).
syphilis (9 papers, 2010 to 2026). A contagious bacterial infection caused by the spirochete Treponema pallidum. "We evaluated the serum expressions of IFN, TNF, IL-10, TGF-β1 and IL-17 in men living with HIV (MLWH) and their association with distinct stages of syphilis." (PMID 41901736, 2026). "Some scholars found that such cytokines IL-6, IL-10, TNF-α are involved in the pathogenesis and development of syphilis, with the progression of the disease cellular immune function being somewhat suppressed." (PMID 35669916, 2022). "A study found that the levels of IL-1β, IL-6, and TNF-α were elevated in serum collected from syphilis patients." (PMID 33282751, 2020). "In the present study, we first identified that miR-216a-5p decreased in the plasma of patients with syphilis compared with the healthy control, which was negatively correlated with levels of inflammatory cytokines such as IL-1β, IL-6, and TNF-α." (PMID 31358689, 2019). "The results showed that the miR-216a-5p expression level was negatively correlated with the expression of inflammatory cytokines IL-1β, IL-6, and TNF-α, indicating the potential function of miR-216a-5p in syphilis progression." (PMID 31358689, 2019). "In accordance with previous studies, the inflammatory cytokines IL-1β, IL-6, and TNF-α were found to be significantly up-regulated in plasma of syphilis patients compared with the healthy controls." (PMID 31358689, 2019). "A diagnosis of syphilis in humans and animal models is typically characterized by elevations in both plasma pro-inflammatory (TNFα, IFNγ, CCL4, IP-10) and anti-inflammatory cytokines (IL-10)." (PMID 30253745, 2018). "Moreover, there was a negative correlation between the levels of miR-216a-5p and inflammatory cytokines such as IL-1β, IL-6, and TNF-α, which were dramatically increased in syphilis patients." (PMID 31358689, 2019). "Our study first identified dramatically decreased miR-216a-5p in plasma of syphilis patients compared with the healthy control, which was negatively correlated with the expression of inflammatory cytokines, including IL-1β, IL-6, and TNF-α." (PMID 31358689, 2019). "In addition, GUD and especially syphilis induces a potent inflammatory response, and tumor-necrosis-factor (TNF)-α production, which is a major enhancer of HIV replication." (PMID 20376191, 2010). "To investigate possible inflammatory mechanisms connecting CMV shedding and acquisition of syphilis, we measured levels of selected cytokines and chemokines (i.e., MCP-1, IL-6, TNF-α, Interferon-γ, RANTES, and IP-10) in seminal plasma." (PMID 26061824, 2015).
systemic juvenile idiopathic arthritis (9 papers, 2007 to 2026). "They found that children with systemic onset JIA (SoJIA) who did received anti-TNF therapy displayed over-expression levels of IFN-α-regulated genes in their blood leukocytes compared with patients without anti-TNF therapy." (PMID 17625003, 2007). "We collectively conclude that full-blown manifestations of Still's disease had been partially masked by prior TNF-blocking therapy and that cessation of TNF-blocking agent and the catastrophic event, that is, motorcycle accident, likely unveiled a flare of Still's disease culminating in MAS." (PMID 27818826, 2016). "Furthermore, TNF-α immunomodulators have previously been used as a common treatment for RA and IL-1β immunomodulators are effective with other chronic diseases such as systemic-onset juvenile idiopathic arthritis and in adult onset Still's diseases." (PMID 21858242, 2011). "At this point, it is worth presenting unpublished data on a historical control of adult patients with Still's disease followed up in our department and treated with TNF inhibitors (infliximab n = 4, etanercept n = 2, adalimumab n = 1), and (n = 5) or MTX (n = 6)." (PMID 21682863, 2011).
venous ulcers (9 papers, 2021 to 2025). "Additionally, a recent study showed that patients with venous ulcers of the lower limbs had higher expression of pro-inflammatory cytokines such as tumor necrosis factor (TNF)-α and IL-1α in peripheral blood mononuclear cells than controls." (PMID 40103929, 2025). "As an example of potential clinical application, the VeCare device was applied to assay TNF-α, IL-6, IL-8, TGF-β1, S. aureus, and pH in wound fluids collected from five patients with active venous ulcers, once a week for five consecutive weeks." (PMID 34020961, 2021). "The VeCare dressing described previously under biomarker sensing combined biosensors for inflammatory mediators like tumor necrosis factor α (TNF‐α), interleukin‐6, interleukin‐8, growth factor TGF‐β, detection of S.aureus and temperature and pressure in venous ulcers by analysis of the wound fluid." (PMID 39235365, 2024). "Many studies focused on the relationship between TNF-α and venous leg ulcers, with a clear detection of TNF-α in intracapillary monocytes of venous ulcer biopsies and increased levels of TNF-α on the margin of non-healing venous leg ulcers." (PMID 39064129, 2024). "Moreover, platelet-rich plasma (PRP) injection therapy, stem cell therapies, biologic skin equivalents, oxygen therapies, anti-TNF therapy, or negative pressure wound therapy, are advanced venous ulcer therapeutic methods that may support the standard of care." (PMID 40382653, 2025). "Furthermore, stem cell therapies, biologic skin equivalents, platelet-rich plasma therapy, oxygen therapies, anti-TNF therapy, or negative pressure wound therapy are advanced venous ulcer therapeutic methods that may support the standard of care." (PMID 34829797, 2021). "Notably, the concentration ranges of TNF-α (0 to 2 ng ml−1), TGF-β1 (0 to 150 pg ml−1), IL-8 (0 to 30 ng ml−1), and IL-6 (0 to 30 ng ml−1) were based on levels reported in wound fluids from patients with venous ulcer, combined with ELISA results from clinical samples used for this study." (PMID 34020961, 2021).
VEXAS syndrome (9 papers, 2022 to 2025). An adult-onset inflammatory disease that affects only males and is caused by somatic, not germline, mutations. "Anti-IL-1 and anti-TNF agents demonstrated poor efficacy in the management of patients with VEXAS syndrome, compared with other interventions." (PMID 40287866, 2025). "In addition, the use of TNF inhibitors should be restricted in VEXAS patients due to the heightened risk of onco-hematological disorders, reported for both VEXAS syndrome and the use of anti-TNF agents." (PMID 40046741, 2025). "The persistent inflammatory environment in VEXAS syndrome is driven by markedly elevated levels of proinflammatory cytokines, notably interleukin-6 (IL-6), tumor necrosis factor-alpha (TNF-α), and interferon-alpha (IFN-α)." (PMID 40563745, 2025). "The analysis of the peripheral blood from patients with VEXAS syndrome showed highly activated inflammatory signatures in multiple pathways, including tumor necrosis factor (TNF), interleukin-6 (IL-6), and interferon-γ." (PMID 37501758, 2023). "Targeted agents, including anti-IL-1 (anakinra and canakinumab), anti-IL-6 (tocilizumab), anti-tumor necrosis factor α (TNF-α) (adalimumab, infliximab, and etanercept), and Janus kinase inhibitors, have been proposed as possible treatments for VEXAS syndrome." (PMID 36544501, 2022). "Mutant myeloid cells are believed to drive the inflammation in patients with VEXAS syndrome, as analyses have revealed activated inflammatory pathways consistent with myeloid-induced inflammation, including tumor necrosis factor (TNF), interleukin-6 (IL-6), and interferon-gamma (INF-gamma)." (PMID 36879894, 2023). "Since immunologic studies of patient samples and zebrafish models in VEXAS syndrome demonstrated upregulation of multiple cytokine signatures including TNF, IL-6 and IFN-γ, a broad therapeutic approach could be beneficial rather than the specific blockade of single cytokines." (PMID 40124776, 2025). "We included patients with VEXAS syndrome who received treatment with azacitidine, JAK inhibitors, IL-6 inhibitors, anti-IL-1, or anti-TNF agents." (PMID 40287866, 2025). "Tumor necrosis factor-alpha (TNF-α) inhibitors, such as infliximab, adalimumab, and etanercept, have been used as steroid-sparing agents in the management of VEXAS syndrome, though their efficacy appears to be limited." (PMID 39598114, 2024). "We found that anti-IL-1 and anti-TNF agents were ineffective in achieving a desirable response in patients with VEXAS syndrome and should not be prioritized in the treatment strategy." (PMID 40287866, 2025). "The lack of response in most cases raises questions about the role of TNF-α in the pathophysiology of VEXAS syndrome, indicating that TNF-α may not be a primary driver of the inflammatory process in this condition." (PMID 39598114, 2024).
AIDS dementia (8 papers, 2010 to 2024). "In addition, TNF-α has been shown to cause excitotoxicity and neuronal damage in murine HIV encephalitis models." (PMID 34893671, 2021). "For TNF‐α, the degree of staining in the frontal deep WM and the BG correlated with the stage of AIDS dementia complex (p = 0.0001 and p = 0.0017 respectively)." (PMID 38282400, 2024). "Here, we investigated the expression of MIP-2γ in astrocytes, a major source of chemokines in the brain, in response to stimulation with LPS or TNF-α, which have been linked to CNS diseases from EAE to AIDS dementia." (PMID 23234294, 2012).
Anal fistula (8 papers, 2016 to 2026). An abnormal connection between the epithelialised surface of the anal canal and the perianal skin. "The trends suggest that future research hotspots will focus on advances in the treatment of CD anal fistula, including emerging endosurgical treatments such as stem cell therapy and anti-tumor necrosis factor agents." (PMID 39869383, 2025). "The first application of ASCs in anal fistulas was in patients affected by CD, with encouraging results and rates of healing of 50%, in combination with anti-tumor necrosis factor (TNF) agents." (PMID 35252334, 2022). "The objective of the present study was to assess local production of a selected panel of cytokines in anal fistulas, including pro-inflammatory interleukin (IL)-1β and tumor necrosis factor α (TNF-α)." (PMID 27402195, 2016). "Although there is currently no literature on this topic, a short-term study could be considered, such as observing the therapeutic effect of locally applying anti-TNF-α agents after suturing the internal opening of the anal fistula." (PMID 39811351, 2025). "Also, cytokines IL-8, IL-12p40 and TNF-α were present in respectively 70, 33 and 30 % of the anal fistulas." (PMID 27402195, 2016). "Also, the cytokines IL-8, IL-12p40 and TNF-α were expressed in a high number of anal fistulas." (PMID 27402195, 2016).
anaplastic large cell lymphoma (8 papers, 2008 to 2026). Anaplastic large cell lymphoma (ALCL) is a rare and aggressive peripheral T-cell non-Hodgkin lymphoma, belonging to the group of CD30-positive lymphoproliferative disorders, which affects lymph nodes and extranodal sites. "CD30 is a member of the superfamily of tumor necrosis factor (TNF) receptor, which is consistently expressed on HRS cells and anaplastic large cell lymphoma (ALCL) cells." (PMID 37062016, 2023). "Anaplastic large cell lymphoma (ALCL) is a subtype of T cell lymphoma characterized by a mature T cell phenotype and by the expression of CD30, a member of the tumor necrosis factor (TNF) receptor superfamily." (PMID 36698412, 2022). "CD30, a 120 kDa surface phosphorylated protein is a member of tumour necrosis/nerve growth factor receptor (TNF/NGFR) family and constitutively expressed by Hodgkin and Reed-Sternberg (HRS) cells of Hodgkin lymphoma (HL) and the neoplastic cells of Anaplastic Large Cell Lymphoma (ALCL)." (PMID 18218123, 2008).